FLT3 (fms related receptor tyrosine kinase 3)
Diseases named in the same sentence as FLT3 in open-access papers (continued):
Sharing a sentence is not in itself a finding about the gene and the disease.
leukemia (continued). "In this study, we demonstrated a new set of 2,6,9-trisubstituted purine derivatives with broad inhibitory activity on three leukaemia-related tyrosine kinases: Bcr-Abl, BTK and FLT-3-ITD." (PMID 35745866, 2022). "We substantiated the results of the in vitro-treatment of primary patient cells with three additional patient leukemia cells, patient #805 (DNTM3A- and FLT3-ITD-mutant), patient #770 (only DNMT3A-mutant) and #719 (FLT3-ITD)." (PMID 36457063, 2022). "We also load CD33‐targeting RBCEVs with antisense oligonucleotides (ASOs) targeting FLT3‐ITD or miR‐125b, 2 common oncogenes in AML, and demonstrate that the engineered EVs improve leukaemia suppression in in vitro and in vivo models of AML." (PMID 35851970, 2022). "The percentage of GFP‐positive leukaemia cells also reduced significantly in the bone marrow, liver, and spleen of the mice treated with CD33‐targeting RBCEVs loaded with FLT3‐ITD ASO as compared to the control groups." (PMID 35851970, 2022). "While monotherapies already slightly delayed leukemia development in mice transplanted with FLT3-ITD+ MV4–11, co-inhibition of lactate import and ETC complex II significantly further delayed leukemia onset compared to the vehicle group." (PMID 35440568, 2022). "We load the antibody conjugated RBCEVs with ASOs targeting FLT3‐ITD or miR‐125b, 2 common oncogenes in AML, and demonstrate that the treatment with engineered EVs improve leukaemia suppression both in vitro and in vivo." (PMID 35851970, 2022). "Another study has reported that genetic defects in RIP3 converted FLT3-ITD- and RUNXETO-driven myeloproliferative AML in mice by increasing the accumulation of leukemia-initiating cells." (PMID 36170029, 2022). "Taking together, sorafenib-resistant leukemia cells overpresented autophagy markers; inhibition of autophagy partly overcame sorafenib resistance, suggesting activation of autophagy could be an important factor for FLT3 inhibitor resistance in FLT3-ITD-poisitive AML cells." (PMID 35794565, 2022). "HSP90 acts as the molecular chaperone and is highly expressed in several therapy‐resistant leukemia subtypes, thereby ensuring correct protein folding of several oncogenic proteins such as BCR‐ABL1 and FLT3‐ITD." (PMID 35928554, 2022). "We have shown that MRX-2843 can mediate anti-leukemia effects through inhibition of both MERTK and FLT3 in AML models." (PMID 36551626, 2022). "In mixed-lineage leukemia (MLL)-rearranged ALL, the methylation of the tyrosine kinase FLT3 on arginine R972 and R973 by PRMT1 controls leukemia cell maintenance in vitro." (PMID 36358861, 2022). "Another inhibitor of FLT3-ITD-driven AML is AP24534 (ponatinib), which inhibits FLT3 activity and induces leukemia cell apoptosis." (PMID 35854240, 2022). "Two different cooperation models of mutant NPM1 with two different signal transduction genes, FLT3-ITD and NRASG12D, showed rapid leukemia onset in mice." (PMID 34944812, 2021). "(A) MLL-rearranged leukemia lines with genotypes indicated were treated with 100 nM pinometostat (DOT1L inhibitor) or 30 nM tandutinib (FLT3 inhibitor MLN518), and relative growth monitored by CellTiter Glo 2.0 assay on the indicated days." (PMID 34263728, 2021). "In summary, we determined that the combination of gilteritinib plus CUDC-907 potently induces apoptosis in both FLT3-ITD AML cell lines and primary patient samples, and significantly prolonged survival of NSGS mice bearing systemic MV4-11 leukemia." (PMID 34099621, 2021). "Some of them, such as hypomethylating agents, FLT3 and Bcl-2 inhibitors, have been used in combination with DLI, aiming to enhance the graft-versus-leukemia effect." (PMID 35155192, 2021). "We were unable to find co-localization of FLT3-wt with Golgi markers, such as lectin-HPA and GM130, in RS4-11 cells, indicating that ITD leads FLT3 to mislocalize to the Golgi region in leukemia cells." (PMID 34811450, 2021).
leukemia (continued). "MRX-2843 was first developed as a MER/FLT3 dual kinase inhibitor and exhibited MER-dependent anti-leukemia activity in the FLT3-ITD model." (PMID 34721022, 2021). "The mutations of genes encoding mitochondrial enzymes, FMS-like tyrosine kinase-3 internal tandem duplication (FLT3-ITD) and isocitrate dehydrogenase (IDH), play a vital role in leukemia cell survival and chemoresistance." (PMID 34692527, 2021). "In addition to leukemia-driving mutations, we have identified recurrent pathogenic mutations CRLF2 p.F232C (n = 7), TYK2 p.A413T (n = 7), JAK2 p.R683G (n = 4), KRAS p.G12D (n = 4), FLT3 p.Y842C (n = 3) and PTPN11 p.D61V (n = 3), previously frequently found in pediatric ALL." (PMID 34830809, 2021). "There were 7 post-transplant relapses in FLT3 MRD(+)/NPM(+) group, and 2 subjects had leukemia recurrence in FLT3 MRD(+)/NPM(−) group (p = 0.62)." (PMID 32333156, 2020). "We can therefore conclude that, on a mouse model of AML, a HFD enforces the FLT3 signaling pathway on primitive hematopoietic cells and, in turn, improves the oncogenic transformation of MLL-AF9 knock-in cells and the leukemia initiation." (PMID 32999332, 2020). "Despite the development of FLT3 inhibitors, the EMBT Acute Leukemia Working Party recommends performing ASCT in their 2017-ELN risk stratification, but with the accompaniment of post-transplantation FLT3 inhibitor maintenance for at least 2 years." (PMID 33363031, 2020). "It induced degradation of FLT-3 ITD at low nM concentrations and inhibited proliferation of the leukemia cells at < 1 nM, while it showed less activities in cells with D835Y or F691L-mutated FLT-3." (PMID 32404196, 2020). "Activation of STAT5 by FLT3-ITD is required to induce primary cell survival in vitro and leukemia in vivo." (PMID 31963765, 2020). "Using the MOLM-14/Luc/GFP xenograft model, mice were administered daily treatment with FLT3 and CXCR4 inhibitors after achieving high levels of leukemia chimerism in the blood." (PMID 32629802, 2020). "Thus, Gilteritinib may be more potent than other TKIs in the treatment of FLT3 mutant leukemia." (PMID 32565734, 2020). "Activating mutations of the FLT3 gene represent one of the most frequently encountered and clinically challenging classes of AML mutations, which may be due to insufficient eradication of slow cycling leukemia stem cells within the bone marrow microenvironment." (PMID 30841639, 2019). "Given the inevitable development of clinical resistance to TKIs (FLT3 ITD AML in particular), addition of FGFR inhibitors to directly modulate the leukemia niche is a promising approach to improve the durability of response." (PMID 30720426, 2019). "Indeed, about 75% of patients with FLT3-ITD–mutated AML at diagnosis continue to have the ITD mutation at relapse, suggesting that FLT3-ITD may function as the driver mutation responsible for progressing the disease into overt leukemia." (PMID 30651634, 2019). "We also identified a positive correlation between the FLT3-ITD MR and the CXCR4 RFI on the surface of leukemia cells (r = 0.588, P ≤ 0.0001)." (PMID 31434952, 2019). "Luteolin possesses selective inhibitory activity against Fms-like tyrosine kinase 3 (FLT3), a receptor tyrosine kinase highly expressed in AML patients, and induces a strong cytotoxic effect in MV4-11 leukemia cells." (PMID 29649138, 2018). "Thus, considering the high frequency class I mutations (especially in KIT, FLT3 and RAS genes) in CBF-AML, it is likely that CCDC26 disruption could highlight a new class I aberration leading to increased cell survival and proliferation in leukemia." (PMID 29464086, 2018). "FLT3L CAR-T cells exhibited specific cytotoxicity against FLT3+ leukemia cell lines and primary AML cells in vitro, particularly FLT3-ITD leukemia cell lines." (PMID 29716633, 2018).
leukemia (continued). "Nevertheless, the effect of specific cytolysis seemed independent of FLT3 expression level on leukemia cells but relied on whether they carried FLT3-ITD mutation, and the FLT3-ITD-positive leukemia cells were more sensitive to FLT3L-based CAR-T cells than the FLT3 wild-type leukemia cells." (PMID 29716633, 2018). "FLT3 ligand (FL) levels are known to be increased by both FLT3 TKI and chemotherapy treatment of patients with leukemia." (PMID 30250637, 2018). "The following sections summarize the eight top-ranked genes in some of the major drug classes (FLT3, CASP8AP2, L2HGDH, MNT, BAZ2B, MZF1, BEX2, and SMARCA4) that are highly likely to have notable biological significance in leukemia." (PMID 29298978, 2018). "Acknowledging the small patient numbers available, encouraging responses (at least 50% reduction in marrow blasts) were observed in patients with FLT3-ITD (3/6) and MLL-rearranged leukemia (2/2)." (PMID 28881728, 2017). "Preclinical studies showed that inhibition of AXL blocks proliferation of FLT3 mutant and FLT3 wild-type AML cells and also suppresses the leukemic burden of FLT3-ITD+ AML in both a subcutaneous xenograft model and a leukemia engraftment model." (PMID 28516360, 2017). "We show that midostaurin, like the dual FLT3/SYK inhibitors, R406 (tamatinib), and R788 (fostamatinib), inhibits SYK in cell-based models of FLT3-ITD- and activated SYK-driven leukemia to a greater extent than highly targeted inhibitors of FLT3." (PMID 28881711, 2017). "From these research databases, we selected four genes of interest, FLT-3, WT1, Bmi-1, and ABCG2, known as oncogenic and stem cell regulators that participate in leukemia initiation and progression." (PMID 26847520, 2016). "Data were compared to transcriptomes of various other human leukemia models we had generated over the years, including CB CD34+ cells transduced with MLL-AF9, FLT3-ITD, NUP98-HOXA9, STAT5A and KRASG12V." (PMID 27055152, 2016). "Infant leukemias are a subgroup with frequent MLL (KMT2A) rearrangements, FLT3 overexpression and high sensitivity to cytarabine, but dismal prognosis." (PMID 27391351, 2016). "This would at least partly constitute the mechanistic basis for the efficacy and validity of therapeutic strategies currently employed against these leukemias, such as Ph-positive ALL and FLT3-ITD-positive AML." (PMID 27286446, 2016). "Consistent with the results obtained using FLT3-ITD+ Ba/F3 cells, the PI3 kinase and PKA inhibitors reduced p21 expression in human FLT3-ITD+ MV4-11 leukemia cells." (PMID 27387666, 2016). "AML biomarkers NPM1, FLT3, CXCR4, MMP9 and IGF-IR are also present in AML cell derived exosomes, along with mRNAs involved in leukemia development." (PMID 27191983, 2016). "Hence pharmacologic inhibitors of CDK1 may be useful for testing in FLT3-ITD driven leukemia." (PMID 25914884, 2015). "Gene-expression studies have shown high levels of Flt3 in leukemia blasts in infants and children with MLL-rearranged leukemia." (PMID 26484338, 2015). "The BPR1J-340 compound exhibits potent FLT3 inhibitory activity, with a 50% inhibitory concentration (IC50) of 25±5 nM and growth inhibitory effects on FLT3-ITD+ leukemia MOLM-13 and MV4;11 cells with a GC50 value of 3.4±1.5 and 2.8±1.2 nM, respectively." (PMID 24416160, 2014). "Another study showed that wild-type FLT3 is constitutively activated in two-thirds of AML patient samples and in 4 of 13 leukemia cell lines tested." (PMID 25295230, 2014).
leukemia (continued). "To ascertain if the in vitro role of PRL-3 correlated with FLT3-ITD-driven AML tumour burden in vivo, we developed a leukaemia mouse model using the lateral tail vein injection of AML cells." (PMID 23929599, 2013). "This microRNA has been shown to be upregulated in FLT3-ITD positive AML, and is thought to contribute to leukemia growth and aggressiveness in these molecular subsets of AML through downregulation of several targets including PU.1." (PMID 23497456, 2013). "In the same study, we also showed a relatively narrow range of signaling responses in FLT3 ITD samples compared to FLT3 WT AMLs suggesting that the latter represented a more heterogeneous and biologically distinct group of leukemias." (PMID 23431389, 2013). "Although activity of silvestrol on the FLT3 expression was impressive, it is likely that silvestrol as a natural product and an inhibitor of eIF4A has the ability to alter the expression and activity of several other targets that may contribute to the impairment of leukemia growth." (PMID 23497456, 2013). "Synergy was also observed between selective Akt inhibitors and the highly potent and selective FLT3 inhibitor, AC220, against mutant FLT3-positive leukemia cells cultured in RPMI+10% FBS." (PMID 23437141, 2013). "Currently, compounds are in clinical trials as therapies to treat MLL-rearranged leukemia (ALL and AML) and AML harboring FLT3-ITD." (PMID 23847761, 2013). "Recently, FLT3 mutations were reported in 4/57 (7%) of dogs with cytologically and immunophenotypically confirmed ALL, suggesting that this important mechanism of leukemia development and/or progression might be another instance of cross-species conservation of pathogenic mechanism." (PMID 21272320, 2011). "Overall, we identified 117 FLT3 regulated tyrosine and serine/threonine phosphorylation proteins in 3 FLT3-ITD leukemia patients." (PMID 21552520, 2011). "The author and colleagues previously reported that FLT3-ITD expression dissociates PLZF and SMRT, and inhibits the function of PLZF, leading to aberrant gene regulation and abnormal cell growth in leukemia." (PMID 21453545, 2011). "Targeted metabolic interventions reveal a remarkable therapeutic vulnerability: glycolysis inhibition demonstrates selective cytotoxicity against FLT3-ITD leukemic cells while sparing wild-type leukemia and normal cellular populations." (PMID 41003134, 2025). "Beyond the HOXA axis, this oncogenic program also drives the expression of other critical survival genes, such as the anti-apoptotic factor BCL-2 and the stem cell marker FLT3 (FMS-like tyrosine kinase 3), both of which contribute to the leukemia’s survival and chemoresistance." (PMID 41614752, 2025). "In FLT3‐ITD mutant AML, genetic or pharmacological suppression of PRMT1 markedly decreases FLT3‐ITD methylation levels and improves the effectiveness of tyrosine kinase inhibitors in eradicating leukemia progenitor cells." (PMID 41256732, 2025). "Healthy non‐leukemic CD34+ cells and other leukemia cell lines with wild‐type FLT3 exhibited no induction of AXL protein levels when treated with FLT3 TKI, even with differing basal AXL levels across the different cells." (PMID 39395205, 2025). "We transduced FLT3-ITD into MA9 cells and monitored their sensitivity to Setd1b sgRNA with or without cytokines to examine the effects of oncogenic signaling and cytokines on MLL-r leukemia cells." (PMID 40341256, 2025). "Moreover, driver genes, as RAS, FLT3, NPM1, EVI1 and KMT2A shape the interaction between polyamine metabolic pathway and leukemia-supporting functions, resulting in selective vulnerabilities, as unveiled by drugs targeting PRMT5." (PMID 40603833, 2025). "In the syngeneic murine AML model, Setd1b sgRNA expression decreased MLL-r leukemia cell propagation in vivo, even without FLT3-ITD or NrasG12D expression; thus, SETD1B requirement increased in the in vivo environment." (PMID 40341256, 2025).
leukemia (continued). "In non-MLL-rearranged leukemia, such as Npm1c/Flt3-ITD, we have also demonstrated a role for leukemia-specific interactions of COMPASS complexes with TFs resulting in altered accessibility at Stat5a and Runx2 loci and consequent transcriptional dysregulation." (PMID 40523422, 2025). "Concurrently, Dovitinib, targeting FLT1, EGFR, FLT3 and KIT, acts as a EGFR inhibitor and FLT3 inhibitor, with previous research showing Dovitinib showed treatment efficacy in naïve and imatinib-resistant BCR::ABL(+) leukemia cells." (PMID 39247833, 2024). "Our previous study demonstrated that USP9X inhibition in FLT3-ITD-positive AML induced the K63-Ub processing of receptor-type tyrosine kinases to form aggresomes, suggesting a rapid removal mechanism for the misfolded proteins in leukemia cells." (PMID 39408703, 2024). "In contrast, favorable risk is defined by mutated NPM1 without concomitant FLT3-ITD mutation, bZIP in-frame mutated CEBPA as well as core-binding factor leukemias." (PMID 38571944, 2024). "Our data point to a novel finding: that diet composition augments doxorubicin efficacy in FLT3‐ITD AML in vivo, indicating that a diet based behavioral modification concurrent with leukemia treatment may have clinical application." (PMID 38334474, 2024). "In a clinical study, FLT3 inhibitors effectively reduced the numbers of leukemia blast cells in peripheral blood (PB), but not those in the BM, where the cells were relatively resistant to these drugs." (PMID 38466568, 2024). "Although TET2 mutation alone is not enough to induce leukemia, TET2 loss in combination with FLT3-ITD mutation is found to be sufficient to induce AML in vivo." (PMID 38696033, 2024). "In addition to venetoclax and MIs, FLT3 inhibitors have also exhibited synergy with MIs in MLLr and NPM1 mutant leukemias." (PMID 39336822, 2024). "We next determined the in vivo anti-leukemia efficacy of adavosertib and panobinostat in the OCI-AML3 xenograft model as well as in AML PDX (patient-derived xenograft) models expressing mtNPM1 and FLT3-ITD in NSG mice." (PMID 36977823, 2023). "CG-806 demonstrated superior anti-leukemia efficacy compared to commercially available FLT3 inhibitors, both in vitro and in vivo, regardless of FLT3 mutational status." (PMID 36865133, 2023). "It is hypothesized that in addition to predisposing these patients to a severe course of COVID-19 and high mortality, COVID-19 and FLT3-ITD-dependent autophagy and HIF-1 overexpression may also play a role in progression of leukemia and drug resistance." (PMID 37189112, 2023). "Consistent with previous reports, FLT3 expression was significantly higher in MLL-r leukemia cell lines (n = 11) than in non-MLL-r leukemia cell lines (n = 89) (p < 0.0001)." (PMID 38016946, 2023). "Importantly, Menin inhibition completely blocked disease progression by eradicating leukemic blasts in a patient-derived NUP98::NSD1/FLT3-ITD-positive PDX model, suggesting that the NUP98 fusion drives the leukemia." (PMID 37520776, 2023). "Moreover, high FLT3 expression also conferred preferential sensitivity to FLT3 inhibition, especially in MLL-r leukemia cells." (PMID 38016946, 2023). "Moreover, TQ treatment reduces the upstream effectors of STAT5, such as KIT and FLT3, leading to dephosphorylate STAT5 in leukemia cells." (PMID 35337104, 2022). "Since we observed the induction of antibody responses to both FLT3 and other tumor membrane antigens, along with the activation of T cells, we assessed whether our VRP vaccine strategy targeted lymphoma and leukemia in vivo." (PMID 35686131, 2022). "Mice harboring a Flt3-ITD knock-in allele only develop a mixture of myeloid and lymphoid neoplasms that do not progress into leukemia." (PMID 34903841, 2022).